DNAJC14 (DnaJ heat shock protein family (Hsp40) member C14)
Description:
Regulates the export of target proteins, such as DRD1, from the endoplasmic reticulum to the cell surface.
Synonyms: DRIP78; HDJ3; DNAJ; LIP6; FLJ32792
Tractability: Antibody: UniProt predicts a signal peptide or a membrane-spanning region. PROTAC: ubiquitination databases record sites on it; its protein half-life has been measured.
Gene: Protein-coding gene on chromosome 12 (55,820,746 to 55,830,824, reverse strand). Ensembl gene ENSG00000135392.
Subcellular location: Endoplasmic reticulum membrane
Gene Ontology:
Molecular function: protein binding; dopamine receptor binding; G protein-coupled receptor binding
Cellular component: membrane; endoplasmic reticulum membrane
Genetic constraint (gnomAD): Loss-of-function variants: 12 observed, 71.53 expected, observed/expected ratio (o/e) 0.17, 90% interval 0.11 to 0.27. The upper end of that interval is the gene's LOEUF score, 0.27, which puts it in group 1 of 6, group 1 being the genes least tolerant of losing a copy. Missense variants: 764 observed, 917.28 expected, observed/expected ratio (o/e) 0.83, 90% interval 0.78 to 0.88. Synonymous variants: 350 observed, 338.44 expected, observed/expected ratio (o/e) 1.03, 90% interval 0.95 to 1.13.
Homologues: Orthologues: chimpanzee DNAJC14 (99% identical), macaque DNAJC14 (98% identical), dog DNAJC14 (92% identical), pig DNAJC14 (90% identical), guinea pig DNAJC14 (87% identical), rat Dnajc14 (86% identical), mouse Dnajc14 (86% identical), rabbit DNAJC14 (80% identical), zebrafish dnajc14 (33% identical), tropical clawed frog dnajc14 (21% identical), Drosophila melanogaster CG10565 (7% identical), Drosophila melanogaster P58IPK (7% identical), and 7 more. Paralogues in human: DNAJC13 (13% identical), DNAJC1 (11% identical), DNAJC17 (10% identical), DNAJC16 (9% identical), DNAJC2 (9% identical), DNAJC10 (9% identical), DNAJC7 (8% identical), DNAJC11 (8% identical), DNAJC3 (8% identical), DNAJC18 (8% identical), DNAJC21 (8% identical), DNAJC25 (8% identical), and 8 more.
Diseases named in the same sentence as DNAJC14 in open-access papers:
DNAJC14 is named in the same sentence as 7 diseases in open-access papers, as found by Europe PMC text mining. Sharing a sentence is not in itself a finding about the gene and the disease. The quoted sentences say what the papers report.
viral infections (2 papers, 2022 to 2025). "Our hypothesis was that DNAJC14 levels present in cultured cells were insufficient to initiate replication of a single RNA molecule after virus infection but sufficient to initiate replication after artificial transfection." (PMID 35852352, 2022). "The CD163, ANPEP, DNAJC14, and ANTXR1 knockout pigs proved resistant to viral infections." (PMID 41465565, 2025).
infection (3 papers, 2011 to 2022). The state of being infected such as from the introduction of a foreign agent such as serum, vaccine, antigenic substance or organism. "We realized that the inhibitory effect of DNAJC14 on YFV was diminished at later time points post infection and that inhibition was dose dependent, with higher levels of DNAJC14 resulting in lower levels of virus replication." (PMID 21249176, 2011). "Immunofluorescence analysis demonstrated that endogenous DNAJC14 rearranges during infection and is found in replication complexes identified by dsRNA staining." (PMID 21249176, 2011). "These DNAJC14-deficient cells were resistant against the infection with non-cp strains of all tested pestivirus species, demonstrating that DNAJC14 is indeed an essential and universal cofactor of the pestiviral replication machinery." (PMID 35852352, 2022). "Consistent with this hypothesis, we noticed that the antiviral activity of DNAJC14 diminished at later times after infection or electroporation (Figures." (PMID 21249176, 2011). "These DNAJC14-lacking cells were resistant against infection with non-cp strains of all tested pestivirus species, demonstrating that DNAJC14 is an essential and universal cofactor of the pestiviral replication machinery." (PMID 35852352, 2022).
cancer (1 paper, 2020). A tumor composed of atypical neoplastic, often pleomorphic cells that invade other tissues. "In contrast, the cancer genes HNRNPA1, PPP2RC5, STRAP, DNAJC14, ATF1 showed upregulation in the cell subpopulations GSC and CD133pos./CD15pos. cells and are located in chromosomal regions that had gains in GSC and CD133pos./CD15pos. cells." (PMID 32634135, 2020). "The cancer genes HNRNPA1, PPP2RC5, STRAP, DNAJC14, and ATF1 showed upregulation in GSC and CD133pos./CD15pos. cells and were included in chromosomal regions that showed gains for GSCs and CD133pos./CD15pos.cells." (PMID 32634135, 2020).
DNAJC14 also shares sentences with these, for which no sentence is quoted: asthma (1 paper); fetal growth restriction (1); Pendred syndrome (1); sarcoma (1).